ABCB7 (ATP binding cassette subfamily B member 7)
Description:
Exports glutathione-coordinated iron-sulfur clusters such as [2Fe-2S]-(GS)4 cluster from the mitochondria to the cytosol in an ATP-dependent manner allowing the assembly of the cytosolic iron-sulfur (Fe/S) cluster-containing proteins and participates in iron homeostasis. Moreover, through a functional complex formed of ABCB7, FECH and ABCB10, also plays a role in the cellular iron homeostasis, mitochondrial function and heme biosynthesis. In cardiomyocytes, regulates cellular iron homeostasis and cellular reactive oxygen species (ROS) levels through its interaction with COX4I1 (By similarity). May also play a role in hematopoiesis (By similarity).
Synonyms: ABC7; EST140535; Atm1p; ASAT
Tractability: Small molecule: a structure with a bound ligand is known. Antibody: UniProt predicts a signal peptide or a membrane-spanning region. PROTAC: ubiquitination databases record sites on it; its protein half-life has been measured.
Gene: Protein-coding gene on chromosome X (75,051,048 to 75,156,732, reverse strand). Ensembl gene ENSG00000131269.
Subcellular location: Mitochondrion inner membrane
Subcellular location (Human Protein Atlas): Mitochondria
Pathways (Reactome):
Metabolism: Cytosolic iron-sulfur cluster assembly
Transport of small molecules: Mitochondrial ABC transporters
Gene Ontology:
Molecular function: ABC-type iron-sulfur cluster transporter activity; identical protein binding; protein binding; protein homodimerization activity; ATP binding; ATPase-coupled transmembrane transporter activity; heme transmembrane transporter activity; ABC-type transporter activity; ATP hydrolysis activity
Biological process: intracellular iron ion homeostasis; iron ion transmembrane transport; iron-sulfur cluster export from the mitochondrion; positive regulation of heme biosynthetic process; positive regulation of iron-sulfur cluster assembly; heme biosynthetic process; iron-sulfur cluster assembly; negative regulation of reactive oxygen species biosynthetic process; heme transport; transmembrane transport
Cellular component: ATP-binding cassette (ABC) transporter complex; mitochondrial inner membrane; mitochondrial membrane; mitochondrion; membrane
Gene-disease validity (ClinGen):
ClinGen rates the evidence that ABCB7 causes each of these diseases.
mitochondrial disease (X-linked): Moderate.
Homologues: Orthologues: chimpanzee ABCB7 (99% identical), rabbit ABCB7 (94% identical), pig ABCB7 (94% identical), dog ABCB7 (93% identical), rat Abcb7 (93% identical), mouse Abcb7 (92% identical), guinea pig ABCB7 (92% identical), macaque ABCB7 (91% identical), tropical clawed frog abcb7 (78% identical), zebrafish abcb7 (74% identical), Drosophila melanogaster ABCB7 (51% identical), Caenorhabditis elegans abtm-1 (48% identical). Paralogues in human: ABCB6 (36% identical), ABCB1 (24% identical), ABCB4 (24% identical), ABCB11 (23% identical), ABCB9 (22% identical), ABCB8 (22% identical), ABCB10 (22% identical), ABCB5 (22% identical), TAP2 (21% identical), TAP1 (20% identical).
Diseases named in the same sentence as ABCB7 in open-access papers:
ABCB7 is named in the same sentence as 91 diseases in open-access papers, as found by Europe PMC text mining. Sharing a sentence is not in itself a finding about the gene and the disease. The quoted sentences say what the papers report.
Ataxia (16 papers, 2006 to 2025). Ataxia refers to impaired coordination of voluntary muscle movement. "We also discuss the possible molecular mechanism linking ABCB7 gene mutations to sideroblastic anemia and ataxia." (PMID 34354969, 2021). "Inherited in an X-linked recessive pattern, patients with defects in ABCB7 gene present clinically with ataxia and sideroblastic anemia in early childhood." (PMID 28064324, 2017). "X-linked SA with ataxia is characterized by spinocerebellar ataxia in male patients that can develop as late as 45 years and is associated with anemia appearing in infancy due to a mutation in ATP-binding cassette transporter ABCB7." (PMID 38355710, 2024). "While the involvement of the human ortholog of Atm1 (ABCB7) in transporting the intermediate to the cytosol remains to be clarified, ABCB7 has been implicated in several iron-related disorders, such as X-linked sideroblastic anemia and ataxia." (PMID 34571846, 2021). "Moreover, a rare inherited X-linked sideroblastic anemia with spinocerebellar ataxia, characterized by anaemia with mitochondrial iron accumulation in the bone marrow erythroblasts, is caused by mutations in ABCB7 gene." (PMID 24592338, 2014). "Interestingly, there was decreased expression of ABCb7, the gene responsible for X-linked hereditary SA with ataxia, a component required for iron-sulfur cluster biogenesis." (PMID 21326867, 2011). "ABCB7 is essential in mice, and in humans, ABCB7 mutations cause X-linked sideroblastic anemia and ataxia (XLSA/A), a rare disorder characterized by an early-onset of non- or slowly progressive spinocerebellar ataxia and mild to moderate anemia." (PMID 26728034, 2016). "However, as with frataxin depletion, hypersensitivity to oxidative stress has been reported in ABCB7 mutants, suggesting that a common mechanism resulting in impaired handling of reactive oxygen species may be involved at some point in both types of ataxia." (PMID 21985033, 2011).
anemia (11 papers, 2007 to 2025). A reduction in the number of red blood cells, the amount of hemoglobin, and/or the volume of packed red blood cells. "We also evaluated genes associated with mitochondrial function (Abcb7, Alas2, and Sod2), which may possibly explain the anemia phenotype in Sf3b1+/− mice." (PMID 25481243, 2014). "ABCB7 function is somehow required for erythropoiesis, as ABCB7 deficient animals develop anemia." (PMID 20862391, 2010). "Hemizygous variants in ABCB7, ALAS2, and MAGED2, associated with X-linked recessive disorders (sideroblastic anemia and antenatal Bartter syndrome), can manifest with hydrops or anemia in utero in affected males." (PMID 41256177, 2025). "Studies has suggested that ABCB7 plays a role in heme biosynthesis and could result in anemia if it expresses exception." (PMID 29377917, 2018).
sideroblastic anemia (11 papers, 2008 to 2025). "Deficiency of the iron transporter ABCB7 is associated with sideroblastic anemia, with ring sideroblasts from intracellular iron accumulation in erythrocytes." (PMID 32660103, 2020). "One such protein Abcb7 is involved in both iron and heme metabolism as mutations in Abcb7 result in sideroblastic anemia." (PMID 26287972, 2015). "In fact, the responsiveness to pyridoxine seen in XLSA also helps to distinguish it from other congenital causes of inherited sideroblastic anemia with mutations in SLC25A38, ABCB7, GLRX5, PUS1, and SLC19A genes." (PMID 39995829, 2024). "The other genetic and secondary etiologies of sideroblastic anemia, which do not involve mutations in the ABCB7 protein, are also described." (PMID 38929857, 2024). "Defects in δ–Alas2, Abcb7 [ATP-binding cassette, sub-family B (MDR/TAP), member 7], Glrx5 [glutaredoxin 5 homolog (S. cerevisiae)] and Slc25a38 (solute carrier family 25, member 38) are causal to different forms of sideroblastic anemias." (PMID 24124461, 2013). "Here, we expound on the relevance of ABCB7 as a clinically important ABC transporter and a rare participant in the disease process of Sideroblastic anemia." (PMID 38929857, 2024). "We suggest that down-regulation of the iron transporter ABCB7 plays an important role in the molecular pathogenesis of RARS, making an intriguing link between the inherited and acquired forms of sideroblastic anemia." (PMID 18398482, 2008). "Moreover, in contrast to canonical SF3B1 mutations, E592K induces a unique RNA missplicing pattern, retains an interaction with the splicing factor SUGP1, and preserves normal RNA splicing of the sideroblastic anemia genes TMEM14C and ABCB7." (PMID 37090662, 2023).
X-linked sideroblastic anemia (9 papers, 2011 to 2025). "On the other hand, ABCB7 restores iron homeostasis and cytochrome levels, and is implicated in heme biosynthesis through interactions with FECH, and ABCB7 mutations are associated with X-linked sideroblastic anemia and mitochondrial iron overload." (PMID 41007630, 2025). "ABCb7, previously shown to be mutated in X-linked sideroblastic anemia with ataxia (XLSA/A—OMIM 301310) is decreased in Sod2-/- cells (1.6 fold decrease, p = 0.02, unpaired t test)." (PMID 21326867, 2011).
X-linked sideroblastic anemia with ataxia (6 papers, 2011 to 2026). A rare syndromic, inherited form of sideroblastic anemia in which the cause of the disease is a mutation in the ABCB7 gene and is characterized by mild to moderate anemia (with hypochromia and microcytosis) and early-onset, non- or slowly progressive spinocerebellar ataxia. "Mutations in ABCB7 are linked to X-linked sideroblastic anemia with ataxia (XLSA/A)." (PMID 42103889, 2026). "Correspondingly, deficiency of such proteins will increase the MLIP, which has been shown for yeast Atm1 raising the mitochondrial iron content by about 30-fold and also holds true for ABCB7 deficiency in humans causing the rare hereditary disease X-linked sideroblastic anemia and ataxia (XLSA/A)." (PMID 25970586, 2015). "X-linked sideroblastic anemia with ataxia (XLSA/A) is a rare X-liked inherited disease, which was linked to the ABCB7 gene mutations." (PMID 34354969, 2021).
iron overload (4 papers, 2011 to 2025). "ABCB7 was found to interact with mitochondrial complexes IV and V. We conclude that in chronic pressure overload, ABCB7 deficiency results in iron overload and mitochondrial dysfunction, contributing to heart failure." (PMID 31511561, 2019).
congenital sideroblastic anemia (3 papers, 2021 to 2025). "In SF3B1K700E expressing cells, ABCB7 and ALAS2, known causative genes for congenital sideroblastic anemia, were downregulated." (PMID 36028755, 2022). "Congenital sideroblastic anemia (CSA) is most frequently caused by X-linked mutations in ALAS2 (Delta-aminolevulinate synthase 2, XLSA), followed by ABCB7 (ATP Binding Cassette Subfamily B Member 7), SLC25A28 (Solute Carrier Family 25 Member 28) and GLRX5 (Glutaredoxin 5)." (PMID 33672223, 2021). "The patient S5 from the secondary group with rather low neutrophil movement velocity was diagnosed with congenital sideroblastic anemia (mutation c.383A>T in ABCB7 gene) and therefore may not be representative." (PMID 41465385, 2025).
diabetes (3 papers, 2014 to 2025). "Further, MFHAS1 and IQGAP2 have some known association with diabetes or related disorders, whereas the other three genes: ZMYM3, HSD17B10 and ABCB7 have no known direct association with diabetes." (PMID 41462339, 2025).
leukemia (2 papers, 2007 to 2024). A malignant (clonal) hematologic disorder, involving hematopoietic stem cells and characterized by the presence of primitive or atypical myeloid or lymphoid cells in the bone marrow and the blood. "ABCB7 is misspliced and down-regulated in SF3B1-mutated leukemia, creating a vulnerability to copper ionophores." (PMID 38517966, 2024). "Artesunate treatment of human CCRF-CEM leukemia and MCF7 breast cancer cells induced ABCB6 expression but repressed ABCB7 expression." (PMID 17726528, 2007).
myelodysplastic syndrome (2 papers, 2016 to 2022). A clonal hematopoietic disorder characterized by dysplasia and ineffective hematopoiesis in one or more of the hematopoietic cell lines. "In particular, the mis-splicing of ABCB7 has been proposed to drive ring sideroblasts formation in patients affected by myelodysplastic syndromes with SF3B1 mutation." (PMID 36230848, 2022).
refractory anaemia (2 papers, 2015 to 2022). "The expression levels of ABCB7 and MAP3K7 were compared among SF3B1WT-, SF3B1K700E-, and SF3B1non-K700E-MDS patients in both whole cohort and subgroups (Refractory anemia [RA] and RA with ring sideroblasts [RARS])." (PMID 36028755, 2022). "Similar to our findings, the expression levels of ABCB7 and MAP3K7 were significantly lower in SF3B1MUT-MDS patients than in SF3B1WT-MDS patients, which was also confirmed for the cohort excluding CMML (Chronic myelomonocytic leukemia) and RAEB (Refractory anemia with excess blasts)." (PMID 36028755, 2022).
bone marrow failure (1 paper, 2021). "ABCB7 was also found to be critical for hematopoiesis as conditional deletion with Mx1-cre resulted in rapid bone marrow failure with pancytopenia, but the requirement of ABCB7 for the development of specific hematopoietic lineages was not examined." (PMID 34762046, 2021).
cardiac hypertrophy (1 paper, 2019). "Altogether, these results indicate that reduced ABCB7 gene expression associated with cardiac hypertrophy can affect an increase in iron and H2O2 levels, ROS generation, and loss of mitochondrial membrane potential in H9C2 cells." (PMID 31511561, 2019). "Studies after si-IGF1R silencing in H9C2 cells revealed that IGF1R-pAKT1-pS6K1 signaling axis could be a mechanistic link between ABCB7 downregulation associated with cardiac hypertrophy and impaired mitochondrial function." (PMID 31511561, 2019). "To understand the significance of ABCB7 silencing mediated iron overload in cardiac hypertrophy, we had given deferiprone (an iron chelator) treatment to H9C2 cells transfected with either siRNA or siABCB7." (PMID 31511561, 2019). "We observed that knockdown of ABCB7 resulted in an exaggerated hypertrophy response, whereas overexpression of ABCB7 rescued the cells from cardiac hypertrophy." (PMID 31511561, 2019). "To investigate the significance of ABCB7 silencing mediated IGF1R signaling axis in cardiac hypertrophy or mitochondrial dynamics, we silenced the IGF1R gene in H9C2 cells transfected with either siRNA or siABCB7." (PMID 31511561, 2019). "ABCB7 could thus be involved in the modulation of transition from cardiac hypertrophy to failure." (PMID 31511561, 2019). "We also did not explore whether ABCB7 compared to the other ABCB-family members has any unique causative role in cardiac hypertrophy." (PMID 31511561, 2019). "To test the role of ABCB7 in cardiac hypertrophy, we transfected H9C2 cells with ABCB7- targeting siRNA to downregulate ABCB7 or with flag-ABCB7 to induce ABCB7 overexpression and then stimulated the cells with angiotensin II to induce hypertrophy." (PMID 31511561, 2019).
dementia (1 paper, 2025). Loss of intellectual abilities interfering with an individual's social and occupational functions. "The aim of this study was to assess the usefulness of ABCA1, ABCB7, ABCB1, APOE, CYP46A1, and LRP1 genotyping as promising dementia risk factors among a wide group of patients diagnosed first with hyperlipidemia." (PMID 41226793, 2025).
depression (1 paper, 2025). "ABCB7 is associated with depression, which is one of the side effects of TELMI." (PMID 40940770, 2025).
erythroleukemia (1 paper, 2007). Acute erythroid leukemia characterised by the presence of at least 50% erythroid precursors and at least 20% myeloblasts in the bone marrow. "Mouse erythroleukemia (MEL) cells were used as model to study the role of ABCB6 and ABCB7 during cellular differentiation." (PMID 17726528, 2007).
esophageal cancer (1 paper, 2025). A primary or metastatic malignant neoplasm involving the esophagus. "ABCB7 (ATP-binding cassette subfamily B member 7) knockdown inhibits the TGF-β signaling pathway, inhibits the survival of esophageal cancer cells by inducing cell death." (PMID 40863976, 2025).
glioma (1 paper, 2020). A benign or malignant brain and spinal cord tumor that arises from glial cells (astrocytes, oligodendrocytes, ependymal cells). "ABCB7 is a mitochondrial iron transporter, and the expression of ABCB7 is associated with the prognosis of glioma patients." (PMID 33489900, 2020).
left ventricular hypertrophy (1 paper, 2019). Enlargement of the LEFT VENTRICLE of the heart. "To examine whether ABCB7 loss associated with hypertrophy, contributes to enhanced accumulation of damaged mitochondria or impaired autophagy clearance, we checked autophagy in left ventricular tissues of rats which underwent aorta constriction and developed left ventricular hypertrophy." (PMID 31511561, 2019).
Myelodysplasia (1 paper, 2018). Clonal hematopoietic stem cell disorders characterized by dysplasia (ineffective production) in one or more hematopoietic cell lineages, leading to anemia and cytopenia. "Taken together, the splicing alterations in ABCB7 and PPOX were the candidates that might be responsible for ring sideroblast formation in SF3B1-mutated myelodysplasia." (PMID 30194306, 2018).
oesophageal cancer (1 paper, 2023). "In oesophageal cancer, ATP-binding cassette, sub-family B (MDR/TAP), member 7 (ABCB7) knockdown inhibits TGF-β signalling pathway transduction by promoting SMAD7 expression and repressing SMAD3 expression, inducing apoptosis and suppressing EMT in oesophageal cancer cells." (PMID 37685308, 2023).
ovarian carcinoma (1 paper, 2023). A malignant neoplasm originating from the surface ovarian epithelium. "The expression of ALAS2 and HMBS involved in iron utilization was associated with improved PFS in ovarian cancer, whereas expression of ABCB7, ALAD, FXN, UROS, ISCU, and CPOX in this process was associated with poor PFS in ovarian cancer." (PMID 38186569, 2023).
tumor (6 papers, 2007 to 2023). "The loss of ABCB7 not only reduces the invasiveness of tumor cells but also results in cell death through dysregulated intracellular iron circulation and mitochondrial ROS generation." (PMID 33489900, 2020). "Relationship between transferrin receptor (TFR), ABCB6, and ABCB7 mRNA expression and response to artesunate (ART) in tumor cell lines of the NCI drug screening panel." (PMID 17726528, 2007).
hematologic disorder (2 papers, 2020 to 2025). A disease involving the hematopoietic system. "Given that ABCB7 dysfunction has been linked to hematologic disorders, in which aberrant splicing of ABCB7 disrupts mitochondrial iron homeostasis." (PMID 41360772, 2025).
ABCB7 also shares sentences with these, for which no sentence is quoted: Obesity (6 papers); liver dysfunction (5); Cirrhosis (4); Liver disease (4); cancer (3); cerebellar ataxia (3); cholestasis (3); infection (3); type 2 diabetes (3); Alzheimer disease (2); cirrhosis of the liver (2); COVID-19 (2); heart failure (2); Hepatic fibrosis (2); hyperglycaemia (2); hyperkalaemia (2); Hypertension (2); Hypoalbuminemia (2); hypocalcaemia (2); Insulin resistance (2); lymphopenia (2); rhabdomyolysis (2); Thrombocytopenia (2); uremia (2); acute coronary syndrome (1); alcohol abuse (1); amyotrophic lateral sclerosis (1); arachnoid cyst (1); Bartter syndrome (1); breast carcinoma (1).
A further 37 diseases each share a sentence with ABCB7 in 1 paper.